CTLA4 (cytotoxic T-lymphocyte associated protein 4)
Diseases named in the same sentence as CTLA4 in open-access papers (continued):
Sharing a sentence is not in itself a finding about the gene and the disease.
tumor (continued). "In this regard, we found that CTLA-4 mAb could directly suppress proliferation and induce apoptosis of tumor cells." (PMID 28099147, 2017). "Starting from the success of anti-CTLA-4 antibody in malignant melanoma, targeted immunotherapy has become one of the effective strategies for anti-tumor therapy, and raised a new wave of research on tumor immunotherapy." (PMID 29061217, 2017). "Similarly, staining intensity for CTLA-4 in the different cell types in the stromal compartment (S-CTLA-4) was relatively homogenous within each tumor, and CTLA-4+ cells were dominated by cells morphologically consistent with immune cells." (PMID 28707078, 2017). "CTLA4 tumor expression is a poor prognostic factor (p=0.05)." (PMID 28038471, 2017). "We combined the data acquired for mLama4- and mAlg8-specific TILs from tumour-bearing mice undergoing anti-CTLA-4 treatment together with data acquired from isotype mAb-treated mice to produce an overall map of all observed phenotypic profiles of tumour-specific TILs." (PMID 28916749, 2017). "CTLA‐4 blockade in mice bearing inoculated tumors enhances anti‐tumor T‐cell responses resulting in tumor rejection, illustrating that releasing the brake on T cells might be an interesting strategy to combat cancer." (PMID 28028012, 2017). "We observed that in our in vitro generated tumor-microenvironment, CTLA4+ ‘exhausted’ T cells percentage were very low (<1%) as compared to FOXP3+CTLA4+CD8+ Treg cells (6.5%) and this indicated that isolated CD8+CD25+CTLA4+ T cell population predominantly comprised of CD8+ Treg cells." (PMID 28487507, 2017). "Moreover, exhausted T-cells express inhibitory surface receptors as CTLA-4, PD-1, BTLA4, CD160, LAG-3, Tim-3 and VISTA among these, CTLA-4 and PD-1 down-regulate the immune activity and are actually targeted to restore the anti-tumor immunity." (PMID 29285320, 2017). "However, better understanding of the tumor microenvironment can lead to elucidation of the actual role of CTLA4 in OSCC prognosis." (PMID 28174608, 2017). "Upon subsequent treatment with anti-CTLA-4, the transferred cells expanded and generated partial responses that laid the foundation for follow up studies including Adoptive Cell Therapy InVigorated to Augment Tumor Eradication (ACTIVATE): Cohorts 1–3." (PMID 28653584, 2017). "We characterized the expression of the immunologic markers MHC Class I and B2M and the T cell inhibitory ligands PD-L1 and cytotoxic T lymphocyte antigen-4 (CTLA-4) by gene analysis on tumor and cell line microarrays and determined cell line protein expression of these markers by flow cytometry." (PMID 29137242, 2017). "Clarification of whether the differences of the clinical performances of these two MAbs is due to the V segment dependent CTLA-4 targeting or Fc mediated ADCC/CDC activity is critical for the understanding of anti-CTLA-4 tumor immunotherapy." (PMID 28978021, 2017). "Sustained overexpression of CTLA-4 is often induced in chronic inflammation and cancer, implying that CTLA-4 in the tumor microenvironment may be involved in dysregulation of the immune response in cancer." (PMID 28707078, 2017). "Moreover, secreted factors from tumor cells also increase the expression of programmed cell death 1 ligand (PD-L1) and cytotoxic T lymphocyte antigen 4 (CTLA-4) ligands in monocytes and macrophages." (PMID 28848446, 2017). "The data presented here indicates already hypomethylated PDCD1 (PD1) and CTLA4 CpGs in the tumor cells, which could be of influence when addressing such kind of treatments." (PMID 28503213, 2017). "This study supports that the radiation regimen, site of RT and tumor characteristics may all contribute to the synergistic effects of RT and anti-CTLA-4." (PMID 28222111, 2017).
tumor (continued). "For instance, the use of DNA hypomethylating agent (5-aza-2’-deoxycytidine) in combination with anti-CTLA-4 monoclonal antibody in syngeneic transplantable murine models demonstrated significant reduction in tumor volumes as compared to single agent treatment alone." (PMID 28148257, 2017). "Immunomodulation of the expression of cell surface receptors such as CTLA4, PD-1, and 4-1BB may be capitalized on to thus yield a T cell immune response in order to achieve an anti-tumor response." (PMID 29179527, 2017). "Importantly, CSF-1R blockade in combination with antibody against PD-1 or CTLA-4, in addition to gemcitabine, led to strengthened tumor regression." (PMID 29299180, 2017). "However, when this was combined with antibodies directed against the CD8+ T cell inhibitory receptors PD-1 and CTLA-4 as well as the inhibitory ligand PD-L1 we were able to obtain long-lasting protection from the B16-OVA tumor in 70% of C57BL/6 mice." (PMID 29072624, 2017). "Zamarin and others demonstrated in mouse models that localized immunotherapy with oncolytic NDV combined with anti-CTLA4 Ab could cure the majority of treated tumor-bearing mice, while treatment with NDV alone was effective in only 10% of cases." (PMID 28555136, 2017). "As expected, PTT based on PLGA-PEG-ICG-R837 together with CTLA-4 blockade could obviously delay the growth of secondary tumours, offering an obviously prior therapeutic effect compared with other control groups." (PMID 27767031, 2016). "Moreover, the 3-year D-FFS in the low tumor CTLA-4 expression group was higher than that in the high tumor CTLA-4 expression group (85.8% vs. 72.3%, p = 0.006)." (PMID 26918337, 2016). "However, when we combined anti-PD-L1 and anti-CTLA-4 to treat mice with tumours after NIR-induced photothermal ablation with PLGA-ICG-R837, more than a half of mice died while no mice died after PLGA-ICG-R837-based PTT combined with single checkpoint blockade." (PMID 27767031, 2016). "In multiple syngeneic mouse tumor models, blockade of PD-1 or its ligands promotes antitumor activity; anti-PD-1 activity in vivo can be enhanced by combination with antibodies to other T cell-negative regulators, such as CTLA-4 and LAG-3." (PMID 27234522, 2016). "A potential target for an miRNA mimic in ICB is miR-138, which has been demonstrated to target both CTLA-4 and PD-1, inhibiting tumor-infiltrating T-regs and subsequently releasing the brake set by these immunosuppressive cells within the glioblastoma microenvironment." (PMID 27774435, 2016). "Treatment of tumor-bearing mice with anti-CTLA-4 antibodies capable of depletion have been shown to substantially reduce Tregs in tumors but not in the periphery, resulting in potentiated antitumor activity as compared to antibodies that lack effector function." (PMID 27610613, 2016). "Combinatorial therapy using Survivin as vaccine and immune checkpoint blockade (PD-1, CTLA-4 etc.)may also be considered for an efficient anti-tumor immune response." (PMID 27340370, 2016). "As number of studies showed that BRAF inhibition increased the number of intratumoral cytotoxic T cells and increased expression of tumor-associated antigens on tumor cells, it was hypothesized that BRAF inhibition could synergize with CTLA-4 blockade." (PMID 27075584, 2016). "Poor Th1 response may be explained by T cell inhibition, either by T-cell tolerance to tumor antigens (PD-1 and CTLA-4 pathways) or increased pro-apoptosis of CD4+ T cells (Fas pathway)." (PMID 27766079, 2016). "Dual blockade of PD-1 and CTLA-4 increased T-cell activity and tumor regression." (PMID 27904752, 2016). "Therefore, both CD8+ CTL/Treg ratio and CD4+Teff/Treg ratios were greatly enhanced in secondary tumours of mice after PLGA-ICG-R837-based PTT plus anti-CTLA-4 treatment." (PMID 27767031, 2016). "It was found that CTLA-4 blockade therapy could greatly reduce the percentages of Tregs (CD3+CD4+Foxp3+) in secondary tumours." (PMID 27767031, 2016).
tumor (continued). "In addition, IDO has been identified as a critical resistance mechanism in anti-tumor immunotherapy targeting the immune checkpoint CTLA-4." (PMID 27192116, 2016). "Indeed, combinational blockade of CTLA-4 and PD-1 revealed a subset of weak-responders to anti-tumor activity." (PMID 26741490, 2016). "Monoclonal antibodies targeting CTLA4 can increase T cell function and induce tumor regression." (PMID 27845904, 2016). "Similar to the PD-1 pathway, the CTLA-4 checkpoint pathway also may be utilized by tumor cells expressing the CTLA-4 surface receptor to counteract the activity of T stimulation." (PMID 27766079, 2016). "The 3-year overall survival (OS) rate (91.4% vs. 81.2%,p = 0.043), failure-free survival (FFS) rate (82.8% vs. 68.0%, p = 0.009) and distant failure-free survival (D-FFS) rate (85.8% vs. 72.3%, p = 0.006) in the low tumor CTLA-4 expression group was higher than in the high tumor CTLA-4 group." (PMID 26918337, 2016). "After adjusting for the UICC stage and other important factors including gender, age, smoking status, first-degree family history of NPC, BMI, and CRP level, a Cox regression analysis confirmed the prognostic value of the tumor CTLA-4 expression, particularly the D-FFS, in NPC patients." (PMID 26918337, 2016). "First, when the ICOS+ Teff to ICOS+ Treg ratio was measured mice receiving CTLA-4 blockade alone had a large tumor burden, thus the shift in ICOS+ Teff to ICOS+ Treg populations may no longer have been apparent." (PMID 26961085, 2016). "In addition, our analyses reveal that elevated tumor cell CTLA-4 expression is associated with shorter OS, and that increased CTLA-4+ TIMC density also increases the risk of death (relative risk of 3.58)." (PMID 27050369, 2016). "Furthermore, the combination of αCD40 plus chemotherapy increased sensitivity to PD-1 / CTLA4 blockade, driving T cell-dependent anti-tumour immunity in a subcutaneous transplantable KPC model, and improving overall survival in the spontaneous KPC model." (PMID 26918344, 2016). "Similarly, treatment with either CTLA-4 or PD1 blocking antibodies increased lymphocyte infiltration in tumor tissues." (PMID 27713158, 2016). "However, while CTLA-4 mainly affects naïve T cells, PD-1 is more broadly expressed on immune cells and regulates mature T cell activity in peripheral tissues and in the tumor microenvironment." (PMID 26881264, 2016). "Tumor engagement of the CTLA-4 pathway may therefore dampen the immune response in the microenvironment resulting in an inappropriate T cell costimulation." (PMID 27809856, 2016). "To address whether alterations in checkpoint molecules in IDO-deficient mice would be recapitulated in response to combination therapy, we analyzed CD8+ lymphocytes within the tumor for immune checkpoint molecules PD-1, CTLA-4, LAG-3, and TIM-3." (PMID 27705910, 2016). "Blocking antibodies to CTLA-4 have induced antitumor activity in syngeneic mouse tumor models." (PMID 27610613, 2016). "Similarly, its multivalent version resulted in enhanced anti-tumor immunity and tumor regression with comparable potency to that of CTLA-4 antibody." (PMID 26863567, 2016). "As a result of over a century’s efforts to understand the role of the immune system in controlling cancer, immunomodulation by checkpoint inhibitors (targeting both CTLA-4 and the PD-1/PD-L1 axis) induced a durable tumor response in a wide range of malignancies." (PMID 26788324, 2016). "However, the clinical implications of CTLA-4 expression in tumors or immune cells in the tumor microenvironment are still controversial, and the potential for CTLA-4 as a prognostic marker has been complicated by differences in study populations and methods." (PMID 27050369, 2016). "Although it has not been seen in GBM, combination therapy with ipilimumab (anti-CTLA-4 antibody) and local radiation has also been shown to cause tumor regression at both irradiated and nonirradiated sites—the latter known as the abscopal effect." (PMID 26881264, 2016).
tumor (continued). "Tumor cells frequently engage CTLA-4 or PD1 to modulate T-cell activity and escape immunodetection." (PMID 29034103, 2016). "CTLA-4 blockade broadens the immune response, evidenced by an increased T-cell receptor repertoire leading to increased tumor infiltration, whereas PD-1 blockade induces intratumoral T-cell proliferation without detectable changes in the peripheral immune repertoire." (PMID 26767073, 2016). "TMEM173 might also play a role in the anti-tumor effect through influencing checkpoint inhibitors such as CTLA4 and PD1." (PMID 27814372, 2016). "Different co-stimulatory (e.g., CD28) and co-inhibitory (e.g., CTLA-4) signal 2 molecules directs differentiation to different avenues, ranging from a potent anti-tumor response (in CD28 activation), to anergy and even apoptosis (upon CTLA-4 or Fas activation)." (PMID 26807257, 2016). "However, if the tumour has become immunoevasive, such as by inducing immunosuppression through CTLA-4, infiltrating CD8+ effector cells will be ineffective." (PMID 26725977, 2016). "Both CTLA-4 and PD-1 are up-regulated upon T cell activation and are hence predicted to constitute significant barriers to the success of therapeutics—including OVs—that endeavour to stimulate anti-tumour immunity." (PMID 26751469, 2016). "Similarly, combinatorial anti-CTLA-4 and RT leads to tumor control in a preclinical model of breast cancer." (PMID 27057463, 2016). "Consistent with this hypothesis, a recent study showed that neutralizing tumor acidity with sodium bicarbonate improved the antitumor efficacy of anti-CTLA-4 or anti PD-1 therapies as well as of adoptive T cell transfer." (PMID 27919264, 2016). "Moreover, treatment with checkpoint blockade antibodies against CTLA-4, PD-1, PD-L1 restores glucose availability in tumour microenvironment, re-establishing the condition for proper T effector cell function." (PMID 27083002, 2016). "In 1996, Jim Allison’s group found that anti-CTLA-4 could boost anti-tumor response of T cell, which proved the immune checkpoint blocking in tumor therapy for the first time." (PMID 27438833, 2016). "Furthermore, antibody therapies targeting CTLA-4 and PD-1 have shown great benefit toward enhancing antitumor immunity resulting in tumor regression and extension of survival in other solid tumor models." (PMID 26925306, 2016). "The value of anti-CTLA-4 monotherapy has been evaluated for many human cancers with varying results; it is likely to be particularly effective for intrinsically immunogenic tumors with a lower tumor burden." (PMID 27741514, 2016). "CTLA-4 expressed by CD4+CD25hiFoxp3+ Treg is thought to contribute to suppression of T effector cells (Teff) and Th, as CTLA-4 deficiency has been shown to decrease both self-tolerance and suppressive function of CD4+CD25+ Treg in tumor immunity." (PMID 27330811, 2016). "The observation that CD39 and CTLA-4 are co-expressed in the majority of intratumoral Treg suggests that these two molecules may be key regulators of functional FoxP3+ Tregs in the tumor." (PMID 27195113, 2016). "Given that irradiation-mediated immune responses alter the tumor micro-environment, more and more researches have explored that local radiation combined with CTLA-4 blockade or PD-L1 blockade could promote anti-tumor immunity." (PMID 27097970, 2016). "The presence of the tryptophan degrading enzyme IDO on APCs or tumor cells may also limit the killing efficacy of CTLA-4 or PD-1 blockade because tryptophan is required for T cell proliferation." (PMID 27847783, 2016). "In mice with colitis-associated colon cancer, Tregs from tumor express higher GARP and CTLA-4." (PMID 27095576, 2016). "In addition, there were significant increases in LAG-3 and CTLA-4 expression in CD8 T cells only in Kras tumours, though the magnitude of induction was less than that observed for TIM-3." (PMID 26883990, 2016).
tumor (continued). "Therefore, further investigation is required to elucidate the effect of the CTLA-4 haplotype on the anti-tumor activity of donor-derived T cells." (PMID 27118383, 2016). "Tumor growth and mean tumor doubling times (TDTs) in these groups (IL-2: 9.7 days, α-PD-1/α-CTLA-4: 6 days, α-PD-1: 8.7 days, α-CD137: 11.7 days, α-PD-1/α-CD137: 11 days) were statistically not significant from Control-treated mice that had a mean TDT of 9.2 days." (PMID 27160390, 2016). "In the CT26 model, tumor-bearing mice treated with anti-CTLA-4 in combination with anti-PD-1 exhibited an increase in the frequency of CD8+ T cells, but not of CD4+ T cells amongst TIL (72% increase in CD8+ T cell frequency relative to control treatment, p<0.01)." (PMID 27610613, 2016). "We found that orthotopic Pan02 tumour-bearing mice were resistant to PD-L1 and CTLA-4 blockade." (PMID 26918344, 2016). "Blockade of CTLA-4 or PD-1 results in pronounced antitumor activity, and monoclonal antibody therapies against these targets improve overall survival in patients with various neoplasias." (PMID 26901565, 2016). "However, recent studies have demonstrated that combination therapy with fractionated RT and CTLA-4 blockade (ipilimumab) or GM-CSF treatment, the percentage of patients showing abscopal tumour regression increased up to 20%." (PMID 27427766, 2016). "Soluble immunosuppressive mediators, including transforming growth factor beta and indolamine 2,3-dioxygenase (IDO), immune regulatory cells, receptor/ligand expression on tumor cells such as CTLA-4 and PD-1/PD-1L and tumor-derived exosomes all serve to dampen T cell activity." (PMID 27071457, 2016). "Moreover, the combination of increased tumor cell CTLA-4 and/or high CTLA-4+ TIMC density is an even stronger predictor of patient outcome (relative risk of 4.53)." (PMID 27050369, 2016). "In addition, lymphocyte CTLA-4 expression, tumor CD28 expression, and lymphocyte CD28 expression were not significant prognostic factors for OS, FFS, D-FFS, or LR-FFS." (PMID 26918337, 2016). "In addition to its anti-angiogenic properties, sunitinib treatment reduces the number of immunosuppressive MDSCs and regulatory T-cells (Tregs) in the tumor and decreases expression of CTLA-4 and PD-1 on tumor infiltrating T-cells." (PMID 27385210, 2016). "Indeed, the presence of tumor-infiltrating lymphocytes is a prerequisite for responses to immune checkpoint inhibitors such as antibodies against CTLA-4, PD-1, and PD-L1." (PMID 27659353, 2016). "However, the MFI of CTLA-4 on the peripheral Tregs was lower than tumor-isolated Tregs, demonstrating differential expression of CTLA-4 expression within tumor Tregs." (PMID 27195113, 2016). "In addition, we also provided evidence to support that miR-143 disinhibited the expression of B7-DC, CTLA4 and PD-1, thereby facilitating tumor immune escaping." (PMID 27626488, 2016). "Tumor CTLA-4 expression was a marginally significant prognostic factor for FFS (p = 0.066)." (PMID 26918337, 2016). "This strategy may also be effective in GBM, as triple therapy with RT combined with CTLA-4 inhibition and 41BB stimulation provides improved tumor control compared to each dual therapy." (PMID 27057463, 2016). "However, a series of interesting anecdotal reports have demonstrated that immune therapy with ipilimumab (human anti-CTLA4 antibody) followed by radiation can lead to extensive tumor regression with increased tumor antigen specific responses." (PMID 27281029, 2016). "The reversal of the exhausted T cell phenotype by CTLA-4/PD-1 blockade is thought to promote T cell mediated killing of tumor cells via T cell recognition of neoantigens that are unique to the tumor cells, and which arise from tumor cell- specific gene mutations." (PMID 27186886, 2016). "Dual blockade of PD-1 and CTLA-4 combined with a tumor vaccine restored T cell activity." (PMID 27050669, 2016).